LIN28A (lin-28 RNA binding posttranscriptional regulator A)
Diseases named in the same sentence as LIN28A in open-access papers (continued):
Sharing a sentence is not in itself a finding about the gene and the disease.
cancer (continued). "Increased tumorigenicity and invasion with increased LIN28A expression can be explained mechanistically by down-regulation of let-7 microRNAs and up-regulation of let-7 targets such as HMGA2, a chromatin modifying gene that is associated with numerous cancers." (PMID 23846349, 2013). "However, LIN28 (A and B) parallel YB-1 in their multiple functions in the cells, in promotion of cancer stem-cell-like characteristics to regulation of splicing." (PMID 24260353, 2013). "miRNA targeted gene pathway interaction identified BCL7A, BCL2L1, LIN28A, KLF6, GATA6, solute carrier family genes and ZNF genes associated with erythropoiesis, cell cycle regulation, glycosphingolipid biosynthesis, cAMP, cGMP-PKG, mTOR, MAPK and PI3K-AKT signaling pathways and cancer pathways." (PMID 36295630, 2022). "Interestingly, LIN28A is associated with specific ribosomal proteins in an RNA-independent mode, and several of these proteins, such as RPL5, RPL10, and RPS27L, have been shown to promote tumorigenesis or cancer." (PMID 34816099, 2021). "Moreover, we observed an important role of LIN28A SUMOylation in promoting cancer progression." (PMID 32333719, 2020). "Of note, under certain conditions, LIN28A/LIN28B may also inhibit cancer cell proliferation." (PMID 26123544, 2015). "Additionally, LIN28A has been found to directly bind E-cadherin mRNA and repress the translation of E-cadherin mRNA in embryo stem cells; however, the role of LIN28Ain directly regulating E-cadherin expression in cancer cells is still unclear." (PMID 26123544, 2015). "For instance, tissue microarrays identified that LIN28A expression was increased in epithelial tumors and promoted cell cycle progression by regulating CDK2, CCND1, and CDC25A in cancer cells." (PMID 34868981, 2021). "LIN28A and LIN28B regulate proliferation by directly or indirectly binding to and affecting the expression levels of cancer growth-related genes, including HER2 and HMGA1, in both let-7-dependent and -independent manners in breast cancer." (PMID 32967226, 2020). "Overexpression of LIN28 has been shown to promote cancer cell proliferation, and PDK1 is critical for LIN28A/B-mediated cancer proliferation as well." (PMID 32560271, 2020). "LIN28A and LIN28B, which negatively regulate members of the let-7 miRNA family, promote cell proliferation in cancers derived from various origins." (PMID 32967226, 2020). "To identify the downstream modulator of TARBP2, we determined the expression of several key factors that have been reported to modulate self-renewal and drug resistance of cancer cells, including SOX2, Nanog, OCT4, Lin28A, CCND1." (PMID 30759864, 2019). "LIN28A and LIN28B expression in cancer is typically mutually exclusive and expression of either gene is almost invariably associated with poor prognosis." (PMID 30057901, 2018). "Lin28a, the transcriptional target of Sp-1, which couldfurther elevate the levels of certain cancer-related miRNAs, was also suppressed by urolithin A in HepG2.2.15 cells.Therefore, we speculated that suppression of Sp-1 could be responsible for thedecrease of Lin28a by urolithin A." (PMID 29742265, 2018). "Overexpression of LIN28A/LIN28B that results in dysregulation of let-7 microRNAs are essential pathological events in tumorigenesis and progression of many human cancers." (PMID 28400788, 2017). "In contrast to the expression of LIN28A/LIN28B proteins, the expression of let-7 family miRNAs is typical decreased in cancers." (PMID 26123544, 2015). "In this review, we summarized the mechanisms of LIN28A/LIN28B and let-7 loop aberrant regulation in human cancer and discussed the roles and potential mechanisms of the LIN28A/LIN28B and let-7 loop in regulating the hallmarks of cancer." (PMID 26123544, 2015). "The RBP LIN28A/LIN28B, a direct target of the let-7 family of miRNAs, is an inhibitor of let-7 biogenesis and is frequently up-regulated in cancers." (PMID 26123544, 2015).
cancer (continued). "LIN28A and LIN28B are stem cell factors that regulate thousands of RNAs and are expressed in aggressive cancers." (PMID 25638158, 2015). "Interestingly, the expression of LIN28A and LIN28B is mutually exclusive in many human cancer cell lines." (PMID 38976670, 2024). "The observation that LIN28A did not rescue was consistent with the lack of LIN28A expression in early cancer lesions." (PMID 38875287, 2024). "In contrast to the localization pattern observed in certain cancer cells, in which LIN28B is more likely to be detected in the nucleus whereas LIN28A localizes to the cytosol, the two paralog proteins appear to localize both in the nucleolus and the cytosol in pluripotent stem cells." (PMID 34331666, 2022). "In this way, the LIN28/Let-7 pathway operates in a double negative feedback loop and overexpression of LIN28A or LIN28B is correlated with cancer progression in several different cancer types including liver, breast, and lung." (PMID 33572600, 2021). "Other interesting examples included AGO4, LIN28A and SMAD2 overmutated in BLCA (an otherwise extremely low-mutation cancer with no mutations in other genes); LIN28B overmutated in SKCM; PRKRA overmutated in OV; and DDX5 overmutated in BRCA and KIRP." (PMID 33406242, 2021). "We confirmed that the mRNA of LIN28A is over-expressed, whereas LIN28A protein level is not altered in cancer cells exogenously expressing the full length of LIN28A mRNA." (PMID 33665193, 2021). "In addition, LIN28A and LIN28B are upregulated in several advanced human cancers and are reliable predictors of a poor prognosis." (PMID 31147574, 2019). "Activation of either LIN28A or LIN28B, two highly related RNA binding proteins (RBPs) and proto-oncogenes, is responsible for the global post-transcriptional downregulation of the let-7 microRNA family observed in many cancers." (PMID 28400788, 2017). "Recent studies suggest that the LIN28A/LIN28B and let-7 loop may also regulate cancer cell immune evasion." (PMID 26123544, 2015). "Although previous reports on RBPs (LIN28A, YTHDFs, and Musashi) have shown that a single inhibition through shRNA, siRNA, or small molecules can suppress cancer stemness, these strategies have not yet been adopted in combination with existing chemotherapies to enhance the effects of chemotherapy." (PMID 39420119, 2024). "Since LIN28A-mediated inhibition of let-7 requires ZCCHC11, small molecules that inhibit functions of this TUTase may also produce therapeutic benefits in cancer patients." (PMID 28400788, 2017). "Although neither LIN28A nor LIN28B are usually present in mature tissues, they are re-expressed in several cancers to support cancer growth." (PMID 38976670, 2024). "In triple-negative breast cancer (TNCB) cells, overexpression of Lin28A/B lowers the level of E cadherin while increasing N cadherin, thereby evidently contributing to EMT development and conferring cancer stem cell characteristics." (PMID 36230562, 2022). "Together with reduced LIN28A and HMGA2 expression, the reduced ability to form spheroids and colonies demonstrates the negative effect let-7 has on the number of cancer stem cells present within these populations." (PMID 34572843, 2021). "For many cancers that appear not to express LIN28AB in the tumor, the CSC population is LIN28A or LIN28B positive." (PMID 28400788, 2017). "As discussed, the expression patterns and functions of LIN28A/LIN28B and let-7 in malignancies are largely opposing and appear to compose a double-negative feedback loop regulating cancer progression." (PMID 26123544, 2015). "While we could not detect LIN28A-stained cells in either tumour or normal tissue, heterogeneous LIN28B protein expression in a subpopulation of cancer cells was found in 3 CCA patient tissues." (PMID 34548635, 2022).
tumor (178 papers, 2011 to 2026). "Compared with the control cells, tumor cells with LIN28A downregulation caused remarkably reduced tumor growth and size in vivo." (PMID 35102250, 2022). "In line with this, LIN28A expression has been reported in different tumor entities, often being associated with increased malignancy." (PMID 34801069, 2021). "This was associated with higher tumor stages and lymph node metastasis, whereas LIN28A knockdown suppressed tumor cell proliferation, invasion, and migration." (PMID 34239534, 2021). "An earlier study demonstrated that LIN28A was abundantly expressed in androgen receptor-positive BC, and their coexpression positively associated with tumor grade and poor prognosis." (PMID 34572725, 2021). "Overexpression of LIN28A/LIN28B is related with advanced disease stage among multiple tumor types and typically associates with poor prognosis." (PMID 28400788, 2017). "Although LIN28A plays important roles in many kinds of tumor cells, the mechanism underlying LIN28A different expression pattern is unclear." (PMID 26910839, 2016). "Abnormally expressed Lin28a can stimulate tumor development and cause cell transformation." (PMID 35453602, 2022). "Other affected genes are related to apoptosis (Ddx20, Ikbip), integrin-associated signal transduccion (Cd47), stress protein with antioxidant-associated tumor suppressive function (Tp53inp1/Trp53inp1), calcium signaling (Stim1), as well as those related to proliferation and survival (Lin28a)." (PMID 30742662, 2019). "Overexpression of Lin28a is linked with induction of tumor growth." (PMID 25457611, 2014). "LIN28A is an RNA-binding protein and a known inhibitor of the let-7 miRNA family, whose components are acting as tumor suppressors." (PMID 40680886, 2025). "In some tumor cells, Lin28a and Lin28b regulated Pdk1 through let-7g to promote glycolysis and inhibit PDH activity." (PMID 39858120, 2025). "In our functional enrichment analysis, we identified several common interacting protein-coding genes within the IGF2BPs gene family including IGF2, HMGA2, and LIN28A/B, all of which are known to facilitate tumor progression." (PMID 40088376, 2025). "The expression of LIN28A was reduced in both tumour subtypes and it was found to be a direct target of MIR9-2-5p in mouse ESCs." (PMID 38693576, 2024). "Lin28a is an RNA-binding protein that can exert its effects by influencing target mRNAs involved in tumor progression." (PMID 39237880, 2024). "Our mechanistic analysis showed that circ_0067557 can play a sponge role in binding to its targets Lin28A and Lin28B, and play an important role in tumor progression and chemoresistance of CRC." (PMID 38216964, 2024). "Tumor cells were diffusely positive for Synaptophysin, CD56, INI1 and SMARCA4 associated with negativity for GFAP, OLIG-2, EMA, BCOR, LIN28A and MIC-2." (PMID 36934287, 2023). "Here, we suggest the novel roles of LIN28A in upregulating genes important for tumor survival by direct binding to cis-elements of their mRNAs, and this upregulation is independent of the degradation of let-7." (PMID 36509142, 2023). "LIN28A is a well-known RBP that degrades the tumor-suppressing miRNA, let-7, by inducing its oligo-uridylation by TUTases." (PMID 36509142, 2023). "LIN28A showed strong immunostaining with nuclear and cytoplasmic localisation limited to the central cells of the tumour island." (PMID 37559082, 2023). "Tumor cells were diffusely positive for Synaptophysin, CD56, INI1, SMARCA4 and ATRX associated with negativity for GFAP, OLIG-2, EMA, BCOR, LIN28A, EZHIP, MIC-2, Cytokeratin’s, SMA, Desmin and Myogenin." (PMID 36934287, 2023). "Overexpression of LIN28A or LIN28B is associated with a variety of tumors, leading to increased tumor aggressiveness and poorer prognosis." (PMID 36831493, 2023).
tumor (continued). "Further characterization of LIN28A expression in TMAs with different BC subtypes revealed that around 50% of the tumor tissues exhibited high LIN28A expression, and its expression ratio with a score > 6 in TNBC was slightly higher compared to other subtypes." (PMID 35102250, 2022). "The human terminal uridyl transferases TUT4 and TUT7 (TUT4/7) catalyze the additions of uridines at the 3′ end of RNAs, including the precursors of the tumor suppressor miRNA let-7 upon recruitment by the oncoprotein LIN28A." (PMID 34949722, 2022). "More importantly, in vivo xenograft assays also revealed that LIN28A-enhanced tumor growth and pulmonary localization were dependent on LIN28/MSI2-mediated YAP1 activation." (PMID 35102250, 2022). "Lin28a overexpression occurs with equal frequency in large fractions of tumors and inhibition of Lin28a and Lin28b via siRNA inhibits tumor growth." (PMID 35453602, 2022). "Numerous studies have found that overexpression of Lin28A/B leads to reduced levels of the let-7 members that stimulate tumour cells to gain stemness and invasiveness." (PMID 36230562, 2022). "In more than 15% of tissue malignancies, either Lin28A or Lin28B is reactivated while let-7 is repressed, resulting in the elevated expression of let-7 target genes as well as alterations in tumor cell metabolism." (PMID 34572067, 2021). "LIN28A is also shown to play a vital role in CSCs, leading to tumor aggressiveness, metastasis, and therapy resistance." (PMID 34572725, 2021). "As a control, enforced expression of LIN28A protein also accelerated tumor metastasis both in vitro and in vivo." (PMID 33665193, 2021). "Based on these observations, Lin28A/B have been proposed as “proto-oncogenes”, whereas Let-7 microRNAs as “tumor suppressors”." (PMID 34573282, 2021). "LIN28A resides on chromosome 1p36.11, which blocks the biogenesis of all let-7s and promotes tumor growth." (PMID 33531982, 2021). "Generally speaking, miRNAs belonging to the let-7 miRNA family have tumor suppressive functions, while LIN28A and the paralog LIN28B, commonly overexpressed in a diverse spectrum of cancers, are considered to be oncogenes." (PMID 32601913, 2020). "Ultimately, there are many pathways that act downstream of LIN28A and likely drive the tumor, providing new opportunities for rationally designed targeted therapies." (PMID 32601913, 2020). "Taken together, these results confirm that SUMOylated LIN28A promotes tumor malignancy by repressing biogenesis of let‐7." (PMID 32333719, 2020). "The expression levels of let‐7s were increased in these LIN28A‐K15R xenografts, indicating SUMOylation of LIN28A promotes tumor progress by suppressing let‐7 biogenesis." (PMID 32333719, 2020). "Histological evaluation of the tumor revealed a primitive high-grade neoplasm, with LIN28A overexpression in the majority of cells by immunohistochemistry, consistent with the diagnosis of ETMR." (PMID 33196040, 2020). "Many studies indicated that both Lin28A and Lin28B show upregulated expression in human malignancies and that they function as oncogenes by promoting transformation and tumor progression." (PMID 30976203, 2019). "We found that mices injected with Lin28A siRNA MDA-MB-453 cells exhibited significantly lower rates tumor growth compared to control cells." (PMID 27494865, 2016). "The expression of Lin28A, AR, and Ki67 in xenograft tumor was detected by using immunohistochemistry." (PMID 27494865, 2016). "The pluripotency factors, such as NANOG, SOX2, OCT4, and LIN28A, suggest a close relationship between tumor formation and the process of reprogramming mature cells to a more primitive type." (PMID 26910839, 2016). "The increased latency of tumor formation that we identified after LIN28A knockdown was likely due to the vast majority of LIN28A knockdown cells being unable to grow." (PMID 25638158, 2015). "LIN28A is essential in induced pluripotent stem cells (iPSC) and represses the let-7 tumor-suppressor miRNA family." (PMID 23533592, 2013).
tumor (continued). "Given the differences between the mouse and human central nervous system, we chose to use human NSCs to model the role of LIN28A in human GBM tumor formation." (PMID 23846349, 2013). "This suggests that long-term activation of this pathway via Lin28A OE, while the inflammatory response is repressed (for example, by dexamethasone treatment), might eventually result in tumor formation." (PMID 39113694, 2024). "Besides, our in vivo experiment indicated that the expression of LIN28A contributed to tumor angiogenesis." (PMID 36509142, 2023). "However, our study shows the potential roles of LIN28A in tumor angiogenesis, which was consistent with the previous findings highlighting the importance of LIN28A expression in tumorigenesis pathologically." (PMID 36509142, 2023). "Moreover, the Lin28A protein was overexpressed in the multilayered rosettes area and the poorly differentiated tumor area in the ETMR tissue." (PMID 36291496, 2022). "The result revealed that LIN28A downregulation significantly decreased tumor incidence." (PMID 35102250, 2022). "There have been many studies underscoring the importance of LIN28A in the regulation of stem cell pluripotency and self-renewal; however, recent investigations have shown abnormal expression of LIN28A in a broad array of tumor types, which is connected to advanced disease and poor prognosis." (PMID 33531982, 2021). "This indicates that Lin28A may contribute to malignant progression of tumor cells but additional factors are necessary to drive ETMR tumor formation in neural precursor cells." (PMID 34801069, 2021). "Thus, above results indicate that LIN28A SUMOylation plays an important role in regulating tumor cell progression." (PMID 32333719, 2020). "As known that LIN28A can promote proliferation, invasion, and metastasis of multiple cancer cells, we wondered whether LIN28A SUMOylation plays a role in regulation of tumor progression." (PMID 32333719, 2020). "Additionally, LIN28A has been found to be highly expressed in CRC tumor tissues and be a potential oncogenic gene in CRC." (PMID 33381451, 2020). "For example, LIN28A facilitated tumor formation, growth, and invasion in ApcMin/+ CRC mice." (PMID 33381451, 2020). "Finally, we further determined that Lin28A promoted tumor growth and metastasis through the interaction with ROCK2 in vivo experiments." (PMID 30266988, 2019). "In addition, by suppressing the expression of lin-28 homolog A (Lin28A), TTP can increase the expression of the tumor suppressor microRNA (miRNA) let-7, whose expression is negatively regulated by Lin28A." (PMID 30380668, 2018). "Both Lin28B and Lin28A specifically interact with the loop sequence of pre-let-7, an interaction that modulates oligo-uridylation and degradation of pre-let-7; the maturation process leads to the well-known post-transcriptional tumor suppressor, let-7." (PMID 27821801, 2016). "LIN28A is known to negatively regulate the tumor-suppressing microRNAs of the let-7 family, and when we performed Nanostring assay for let-7 family members, we found that AT/RT tumors had significantly lower let-7 levels than PA samples (p<0.01 for all let-7 species by Mann-Whitney test)." (PMID 25638158, 2015). "Therefore, we compared expressions of Lin28A and Lin28B in primary OSCCs and analysed their clinical significances, respectively and collectively, in correlation with tumour clinical features and patient clinical outcomes." (PMID 24386298, 2013). "Hence, Lin28a/b reactivation would contribute to the formation of metastasis thereby explaining why Lin28a/b up-regulation correlates with tumor aggressiveness and an advanced tumor stage." (PMID 23939427, 2013).